CDK5 (cyclin dependent kinase 5)
Diseases named in the same sentence as CDK5 in open-access papers (continued):
Sharing a sentence is not in itself a finding about the gene and the disease.
lymph node metastasis (7 papers, 2015 to 2023). "Similar trend was reported in non-small cell lung cancer that CDK5 expression was associated with differentiation, lymph node metastasis and overall survival." (PMID 27406233, 2016). "Another study observed that the overexpression of miR-21 and cyclin-dependent kinase 5 (CDK5) were associated with epithelial-to-mesenchymal transition (EMT) and lymph node metastasis (LNM)." (PMID 31766478, 2019). "The positive relationships were found between CDK5 and lymph node metastasis (P < 0.001), FIGO stage (P < 0.001), TNM stage (P < 0.001) and pathological grade (P < 0.001) in SCC." (PMID 27406233, 2016). "Our results showed that CDK5 expression had a close relationship with lymph node metastasis (r = 0.317, P < 0.001)." (PMID 27406233, 2016). "Study has shown that the expression of miR-21 and CDK5 were correlated with lymph node metastasis in head and neck squamous cell carcinoma." (PMID 27406233, 2016). "Univariate analysis showed significant relationships between the Overall survival (OS) and higher T stage, high expression of CDK5, MiR-21, N-cadherin, Vimentin, low expression of E-cadherin, and lymph node metastasis (p < 0.05)." (PMID 26690371, 2015). "Furthermore, the positive relationships were found between CDK5 and lymph node metastasis (P < 0.001), FIGO stage (P < 0.001), TNM stage (P < 0.001) and pathological grade (P < 0.001) in SCC." (PMID 27406233, 2016). "CDK5 had a positive relationship with lymph node metastasis (r = 0.317; P < 0.001)." (PMID 27406233, 2016). "It was showed that there were close correlations between CDK5 expression and TNM stage (r = 0.155, P = 0.003), lymph node metastasis (r = 0.279, P < 0.001), and pathological grading (r = 0.310, P < 0.001)." (PMID 26860827, 2016). "For instance, higher CDK5 expression was found to be correlated with advanced FIGO stage, advanced TNM stage and lymph node metastasis." (PMID 27406233, 2016). "Spearman coefficient of correlation showed that the positive CDK5 expression in SCLC was correlated with gender (r = 0.418, P = 0.034), TNM stages (r = 0.415, P = 0.049), and lymph node metastasis (r = 0.469, P = 0.024)." (PMID 26860827, 2016). "Analysis showed that the expression of miR-21, CDK5, EMT markers, and lymph node metastasis are closely correlated." (PMID 26690371, 2015). "Recent studies found Cdk5 protein up-regulation in 66 out of 95 (69.5%) NSCLC samples, and that Cdk5 expression correlated with decreased 5-year survival, poor differentiation, lymph node metastasis, and poor prognosis." (PMID 30452490, 2018). "Moreover, in NSCLCs, Spearman analysis revealed that expression of CDK5 was correlated with TNM stages (r = 0.129, P = 0.017), lymph node metastasis (r = 0.365, P < 0.001), and pathological grading (r = 0.307, P < 0.001), respectively." (PMID 26860827, 2016). "Moreover, Spearman analysis showed that the positive CDK5 expression in NSCLC was correlated with TNM stages (r = 0.129, P = 0.017), lymph node metastasis (r = 0.365, P < 0.001), and pathological grading (r = 0.307, P < 0.001)." (PMID 26860827, 2016). "CDK5 expression in patients without lymph node metastasis (52.3 %) was lower than with lymph node metastasis (91.4 %) (P < 0.001)." (PMID 27406233, 2016). "In the patients with SCLC, higher expression of CDK5 was found in female (100 %, 5/5) and lymph node metastasis (76.9 %, 10/13) compared with that in male (47.6 %, 10/21, P = 0.037) and without lymph node metastasis (30 %, 3/10, P = 0.028), respectively." (PMID 26860827, 2016). "However, these clinicopathological variables, such as pathological grade, lymph node metastasis and FIGO stage above only showed weak relevance with SCC, thus, the relationship between CDK5 expression and the clinicopathological parameters needs to be confirmed with larger sample size." (PMID 27406233, 2016).
ovarian carcinoma (7 papers, 2015 to 2024). A malignant neoplasm originating from the surface ovarian epithelium. "Expression of PP1 and Cdk5 was assessed in ovarian cancer, with high cytoplasmic and nuclear PP1 expression associated with adverse survival (P = .005 and .033, respectively)." (PMID 32588513, 2020). "High CDK5 expression is associated with shorter progression-free survival in ovarian cancer." (PMID 37993880, 2023). "The current study sought to determine DARPP‐32, PP1 and Cdk5 expression in ovarian cancer and determine their relationships with patient survival." (PMID 32588513, 2020). "This study investigated the expression of DARPP‐32, PP1 and Cdk5 in a cohort of ovarian cancer patients." (PMID 32588513, 2020). "CDK5 also has been found in the ovary, but only few studies mentioned the role of CDK5 in ovarian cancer." (PMID 26146988, 2015). "In this study, we have shown for the first time that knockdown of CDK5 inhibits growth and increases paclitaxel sensitivity of ovarian cancer cell lines and xenografts." (PMID 26146988, 2015). "Our data demonstrate that patients with high CDK5 expression, especially the cytoplasmic expression have poor overall survival in ovarian cancer." (PMID 26146988, 2015). "CDK5 protein was measured by immunohistochemical staining of an ovarian cancer tissue microarray to correlate CDK5 expression with overall patient survival." (PMID 26146988, 2015). "Conversely, decreased expression of CDK5 has seen in the ovarian cancer cells treated with a curcumin analog that can re-sensitize cisplatin-resistant ovarian cancer." (PMID 26146988, 2015). "Our data document that knockdown of CDK5 with siRNA can induce apoptosis and G1 arrest in ovarian cancer cell lines and xenografts." (PMID 26146988, 2015). "To explore the mechanism by which CDK5 silencing inhibited ovarian cancer cell growth and enhanced paclitaxel sensitivity, we first examined the effect of CDK5 knockdown on activation of AKT by detecting Ser473 phosphorylation of AKT." (PMID 26146988, 2015). "This study explores the mechanisms by which CDK5 regulates paclitaxel sensitivity in human ovarian cancers." (PMID 26146988, 2015). "Our observations in cell culture and in mouse models indicated that knockdown of CDK5 inhibited ovarian cancer cell growth and regulated paclitaxel sensitivity." (PMID 26146988, 2015). "Furthermore, increased expression of CDK5, especially cytoplasmic expression in human ovarian cancers, leads to poor cell survival." (PMID 37993880, 2023). "Using immunohistochemistry, expression of DARPP‐32, PP1 and Cdk5 was determined in a large cohort of primary tumours from ovarian cancer patients (n = 428, 445 and 434 respectively) to evaluate associations between clinical outcome and clinicopathological criteria." (PMID 32588513, 2020). "Roscovitine can inhibit CDK5 and block growth of several ovarian cancer cell lines." (PMID 26146988, 2015). "Increased expression of CDK5 in human ovarian cancers correlates inversely with overall survival." (PMID 26146988, 2015). "Knockdown of CDK5 enhances paclitaxel sensitivity in human ovarian cancer cells." (PMID 26146988, 2015). "CDK5 inhibition can potentiate paclitaxel activity in human ovarian cancer cells." (PMID 26146988, 2015).
ovarian carcinoma (continued). "Protein expression was assessed in ovarian cancer tissue; 428, 445 and 434 patients were available for assessment for DARPP‐32, PP1 and Cdk5, respectively." (PMID 32588513, 2020). "Knockdown of CDK5 with siRNAs inhibits activation of AKT which significantly correlates with decreased cell growth and enhanced paclitaxel sensitivity in ovarian cancer cell lines." (PMID 26146988, 2015). "In this study, we have found that CDK5 knockdown inhibits phosphorylation of AKT, and induces G1 cell cycle arrest, apoptosis and enhanced sensitivity to paclitaxel in ovarian cancer cell lines." (PMID 26146988, 2015). "In summary, CDK5 silencing can induce downregulation of AKT activity, apoptotic cell death and G1 cell cycle arrest in ovarian cancer cells both in cell culture and in xenografts." (PMID 26146988, 2015). "Thus, our data suggest that CDK5 might serve as a prognostic biomarker for ovarian cancer patients." (PMID 26146988, 2015). "In this study, knockdown of CDK5 with siRNAs inhibits activation of AKT which significantly correlates with decreased cell growth and enhanced paclitaxel sensitivity in ovarian cancer cell lines." (PMID 26146988, 2015). "This hypothesis is further supported by results reported in CDK5-inhibited HCC cells and CDK5-depleted ovarian cancer cell lines, in which cancer cells exhibit higher sensitivity to DNA-damaging agents." (PMID 38474332, 2024). "These combined results suggest a loss of DARPP‐32 and/or protein function may be important in ovarian cancer, in particular those with high expression levels of PP1 or Cdk5." (PMID 32588513, 2020). "There is increasing evidence that DARPP‐32, PP1 and Cdk5 have a role in various tumour types; however, expression of DARPP‐32 and PP1 has not previously been described in ovarian cancer, although DARPP‐32 has been implicated in follicular development." (PMID 32588513, 2020). "Multiple ovarian cancer cell lines and xenografts were treated with CDK5 small interfering RNA (siRNA) with or without paclitaxel to examine the effect on cancer cell viability, cell cycle arrest and tumor growth." (PMID 26146988, 2015). "It is possible that CDK5-mediated modulation of AKT may regulate cancer cell survival and chemo-resistant in ovarian cancer." (PMID 26146988, 2015). "Thus, whereas ovarian cancer cell lines can be clearly segregated into PD0332991-sensitive and resistant lines, IC50 values for current CDK2 inhibitors show a continuum within a narrow dose range that may be the result of non-cell cycle CDKs affected by SNS032 (CDK9) and dinaciclib (CDK5, 9)." (PMID 25557169, 2015).
diabetic nephropathy (6 papers, 2016 to 2026). "A recent study implicated CDK5 in renal fibrosis, and elevated p35 was shown to be predictive of fibrosis severity in diabetic nephropathy." (PMID 29535807, 2018). "Therefore, we propose the scientific hypothesis: The CDK5 activity in diabetic nephropathy causes podocyte injury and apoptosis by regulating the NGF/Sirt1 axis and oxidative stress inflammatory factors in podocytes." (PMID 35874807, 2022). "Cyclin-dependent kinase 5 (CDK5) has been documented in podocyte injuries in diabetic nephropathy (DN), however its role in renal tubular epithelial cells has not been elucidated." (PMID 27145370, 2016). "In conclusion, our study demonstrates a novel mechanism that reducing CDK5 activity inhibits tubulointerstitial fibrosis by blocking ERK1/2/PPARγ-mediated EMT in diabetic nephropathy." (PMID 27145370, 2016). "The study also highlighted the role of Cdk5-mediated Sirt1 phosphorylation in mitochondrial dysfunction and podocyte injury in diabetic nephropathy, suggesting that targeting the Cdk5-Sirt1 signaling pathway could be a potential therapeutic strategy." (PMID 39835172, 2025). "In addition, inhibition of Cdk5 overactivation in our diabetic nephropathy model positively regulated the NGF/Sirt1 axis and reduced the HG-induced oxidative stress response and apoptosis in podocytes." (PMID 41181709, 2025). "Sirt1 is a Cdk5 substrate In an HG environment, Sirt1 regulates oxidative stress, reduces inflammation and apoptosis in renal cells, and improves renal interstitial fibrosis in diabetic nephropathy." (PMID 41181709, 2025). "Furthermore Sirt1 is one of the substrates of CDK5, which plays an important protective role in cell differentiation, survival, and anti-oxidation in diabetic nephropathy." (PMID 35874807, 2022). "CDK5 might have therapeutic potential for diabetic nephropathy." (PMID 27145370, 2016). "CDK5 might have therapeutic potential in diabetic nephropathy." (PMID 27145370, 2016). "The present results demonstrated that CDK5 promoted renal tubulointerstitial fibrosis through enhancing phosphorylated ERK1/2 and PPARγ in diabetic nephropathy." (PMID 27145370, 2016).
memory impairment (6 papers, 2011 to 2025). "In AD-OSA, OSA exacerbation is associated with memory impairment and executive dysfunction, P-tau 396 elevation and CDK5 decline in CSF, synaptic disruption, and brain atrophy." (PMID 41403902, 2025). "We next investigated whether rolipram could extend its ameliorative effects to the memory impairment caused by Cdk5 loss of function in hippocampal area CA1." (PMID 21984943, 2011). "Here, we found that endothelial CDK5‐deficit mice exhibited memory impairment and decreased phosphorylation of CaMKII after tamoxifen treatment for 20 weeks and not for 4 weeks." (PMID 35770064, 2022). "P25 is a subunit of the Cyclin-dependent kinase 5 (CDK5) that is elevated in human AD patients and has been linked to amyloid and tau pathology as well as severe neurodegeneration and memory impairment." (PMID 25009454, 2014). "In contrast, rTBI rats treated with 25–106 displayed no significant memory impairment in comparison to uninjured control animals and were significantly improved in mnemonic function compared to animals that received rTBI without Cdk5 inhibition." (PMID 36854738, 2023).
amyloid (5 papers, 2005 to 2025). "APP can also be phosphorylated at Thr668 by CDK5 in neuronal cultures in vitro, suggesting an important role of CDK5 in promoting amyloidosis in AD." (PMID 35740910, 2022). "Because CDK5 phosphorylates tau, APP, and BACE1, a component of the beta-secretase, CDK5 is an important link between amyloid- and tau-pathology." (PMID 23776568, 2013). "In this study, activation of microglia by LPS only affected the tau pathology via cdk5/p25 activation, but not the amyloid pathology, further highlighting the potential pathophysiological changes that can be induced by inflammation in AD." (PMID 16232318, 2005). "Indeed, we observed in the hippocampi of dKI mice a significant increase in NOX1 and phosphorylated JNK/SAPK/total JNK at 6 months, while CDK5 was significantly increased by 12 months, suggesting that the UNC5C T835M-mediated apoptotic pathway was exacerbated by amyloid pathology in dKI mice." (PMID 40468412, 2025).
brain injury (5 papers, 2014 to 2022). Acute and chronic (see also brain INJURIES, CHRONIC) injuries to the brain, including the cerebral hemispheres, CEREBELLUM, and brain STEM. "These facts raise the possibility that zinc may play a role in CDK5 regulation in ischemic brain injury." (PMID 30158515, 2018).
frontotemporal dementia (5 papers, 2018 to 2025). Frontotemporal dementia (FTD) comprises a group of neurodegenerative disorders, characterized by progressive changes in behavior, executive dysfunction and language impairment, as a result of degeneration of the medial prefrontal and frontoinsular cortices. "In frontotemporal dementia (FTD), hyperphosphorylated tau driven by CDK5 and GSK3β causes microtubule destabilization and neurofibrillary pathology." (PMID 41303499, 2025).
head and neck squamous cell carcinoma (5 papers, 2015 to 2025). A squamous cell carcinoma that arises from any of the following anatomic sites: lip and oral cavity, nasal cavity, paranasal sinuses, pharynx, larynx, and salivary glands. "Targeting miR-21 had been reported to regulate CDK5 expression in head and neck squamous cell carcinoma." (PMID 39959665, 2025). "However, the role of STAT3/miR-21 axis and CDK5 in head and neck squamous cell carcinoma remains unclear." (PMID 26690371, 2015). "For example, upregulation of miR-21 has been reported to be correlated with lymph node metastasis in head and neck squamous cell carcinoma (HNSCC) and actives the expression of cyclin-dependent kinase 5 through the STAT3/miRNA-21 pathway, which has also been shown to promote EMT." (PMID 33680908, 2020).